PON2 (paraoxonase 2)
Description:
Capable of hydrolyzing lactones and a number of aromatic carboxylic acid esters. Has antioxidant activity. Is not associated with high density lipoprotein. Prevents LDL lipid peroxidation, reverses the oxidation of mildly oxidized LDL, and inhibits the ability of MM-LDL to induce monocyte chemotaxis.
Tractability: Antibody: UniProt places it where antibodies can reach, with high confidence; its Gene Ontology location is reachable by antibodies, with high confidence; UniProt predicts a signal peptide or a membrane-spanning region. PROTAC: ubiquitination databases record sites on it; its protein half-life has been measured.
Target class: Enzyme; Hydrolase
Gene: Protein-coding gene on chromosome 7 (95,404,861 to 95,435,389, reverse strand). Ensembl gene ENSG00000105854.
Subcellular location: Membrane
Pathways (Reactome):
Metabolism: Synthesis of 5-eicosatetraenoic acids
Gene Ontology:
Molecular function: acyl-L-homoserine-lactone lactonohydrolase activity; protein binding; protein homodimerization activity; arylesterase activity
Biological process: lactone catabolic process; carboxylic acid catabolic process; response to toxic substance
Cellular component: plasma membrane; extracellular region; membrane
Genetic constraint (gnomAD): Loss-of-function variants: 25 observed, 32.53 expected, observed/expected ratio (o/e) 0.77, 90% interval 0.56 to 1.07. The upper end of that interval is the gene's LOEUF score, 1.07, which puts it in group 4 of 6, group 1 being the genes least tolerant of losing a copy. Missense variants: 336 observed, 396.13 expected, observed/expected ratio (o/e) 0.85, 90% interval 0.77 to 0.93. Synonymous variants: 141 observed, 148.23 expected, observed/expected ratio (o/e) 0.95, 90% interval 0.83 to 1.09.
Homologues: Orthologues: chimpanzee PON2 (100% identical), macaque PON2 (98% identical), pig PON2 (94% identical), rabbit PON2 (93% identical), guinea pig PON2 (90% identical), rat Pon2 (90% identical), dog PON2 (89% identical), mouse Pon2 (88% identical), tropical clawed frog pon2 (61% identical), zebrafish pon3.1 (55% identical), zebrafish pon2 (53% identical), zebrafish pon3.2 (53% identical), and 6 more. Paralogues in human: PON1 (66% identical), PON3 (66% identical).
Diseases named in the same sentence as PON2 in open-access papers:
PON2 is named in the same sentence as 123 diseases in open-access papers, as found by Europe PMC text mining. Sharing a sentence is not in itself a finding about the gene and the disease. The quoted sentences say what the papers report.
atherosclerosis (27 papers, 2012 to 2025). A disease characterized by the build-up of fatty material and calcium deposition in the arterial wall resulting in partial or complete occlusion of the arterial lumen. "Insight from murine models underscores the consequential impact of PON2 deficiency, culminating in augmented atherosclerosis attributable to diminished anti-oxidative and anti-inflammatory capabilities." (PMID 39411310, 2024). "PON2 further contributes to lowering ROS production and oxidative stress associated with the development of atherosclerosis when it is located in the mitochondria." (PMID 38397445, 2024). "Similar findings of increased oxidative stress susceptibility with PON2 deficiency have been reported in numerous disease models, including atherosclerosis, heart failure, impaired hepatic insulin signaling, and obesity." (PMID 37891899, 2023). "Previous studies have demonstrated PON2 is a critical antioxidant enzyme, as the loss of PON2 is associated with multiple morbidities in-vivo, such as atherosclerosis, heart failure, impaired insulin signaling, and obesity." (PMID 36056313, 2022). "It is known that inhibition of PON2/3 activity causes the progression of atherosclerosis in humans and mice, and is associated with destabilization of atherosclerotic plaques." (PMID 34017868, 2021). "Serum Paraoxonase 2 (PON2) level is a potential biomarker owing to its association with a number of pathophysiological conditions such as atherosclerosis and cardiovascular disease." (PMID 34714861, 2021). "Previous studies have shown that PON2 exhibits anti-oxidant and anti-inflammatory functions, and PON2-deficient (PON2-def) mice are more susceptible to atherosclerosis." (PMID 30641857, 2019). "Previously, we demonstrated that PON2 deficiency in mice leads to increased atherosclerosis due to decreased anti-oxidative and anti-inflammatory capacity." (PMID 30641857, 2019). "The observation that paraoxonase 2-deficient apoE−/− mice develop enhanced mitochondrial oxidative stress and exacerbated atherosclerosis supports the evidence for a role of disturbed PON activity in vascular injury." (PMID 28058087, 2016). "Risk loci occurred in PON2 that encoded intracellular proteins with antioxidant properties, which normally protect against atherosclerosis and hyperglycemia." (PMID 26169365, 2015). "PON2 deficiency aggravates mitochondrial ROS formation, systemic inflammation, and atherosclerosis." (PMID 29531225, 2018). "Risk loci occurred in PON2, which has antioxidant properties that might protect against atherosclerosis and hyperglycemia, showing it is a susceptible gene for the YZ constitution and possible regulation by 13-hydroxy-(9E_11E)-octadecadienoic acid." (PMID 26169365, 2015). "A common PON2 polymorphism (Cys311Ser) has been associated with an increased risk of cardiovascular disease in individuals with familial hypercholesterolemia, suggesting that genetic variation in PON2 may influence individual susceptibility to atherosclerosis." (PMID 41303537, 2025). "Since several studies have demonstrated that PON2 has a positive effect on atherosclerosis, we aimed to investigate the effect of PON2 on endogenous ASGR1 expression and further explore the follow-up effects of this impact." (PMID 39055948, 2024). "PON2, like PON1, is an enzyme with undefined antioxidant properties, and PON2 deficiency is closely associated with the development of atherosclerosis in a mouse model." (PMID 36509805, 2022). "Studies in the last five years have demonstrated that PON2 protects against atherosclerosis by preventing LDL oxidation, reversing the oxidation of mildly oxidized LDL, inhibiting monocyte chemotaxis, and increasing cholesterol efflux." (PMID 33562328, 2021). "In the following paragraphs we will discuss in detail PON2 involvement in atherosclerosis (Section 6.1), cancer (Section 6.2), insulin sensitivity (Section 6.3), and neurodegeneration (Section 6.4)." (PMID 33562328, 2021).
atherosclerosis (continued). "Cells overexpressing PON2 are less prone to oxidize LDL showing significantly less intracellular oxidative stress when exposed to either H2O2 or oxidized phospholipids, suggesting that PON2 plays a protective role in atherosclerosis." (PMID 33562328, 2021). "PON2 reduces oxidative stress in vascular cells and decreases ER stress-induced caspase activation, thereby protecting vascular function and preventing atherosclerosis." (PMID 33968295, 2021). "The binding of ubisemiquinone to PON2/3 prevents superoxide generation, thereby preventing the development of atherosclerosis." (PMID 33562328, 2021). "Knockout and transgenic mouse models have shown that PON2 protects against the development of atherosclerosis, obesity, insulin resistance, and neurogenerative diseases." (PMID 29531225, 2018). "Despite growing evidence suggesting that PON2 ameliorates atherosclerosis, Type II diabetes, and neurodegenerative diseases, its role in cancer has not been established in an in vivo model." (PMID 29531225, 2018). "Further studies are needed to elucidate if and how GADD45A, NCOR1 and PON2 are involved in the development of accelerated atherosclerosis in RA." (PMID 30138371, 2018). "In summary, our results support the role of PON2 in protecting against atherosclerosis development by shifting the polarization of macrophages toward the M2 anti-inflammatory phenotype." (PMID 26779262, 2015). "PON1 and PON2 were both shown to protect from atherosclerosis development, secondary to HDL-associated PON1 antiatherogenic effects in the circulation and in the arterial wall and to PON2 antiatherogenic effects only in the arterial wall." (PMID 26779262, 2015). "Paraoxonase 2 (PON2) is expressed in macrophages, and it was shown to protect against atherosclerosis." (PMID 26779262, 2015). "PON2 also inhibits the development of atherosclerosis in mice, via mechanisms involving the reduction of oxidative stress." (PMID 24816800, 2014). "PON2 and PON3 are also able to hydrolyze lactones similar to PON1, and they have also been implicated in the atherosclerosis process." (PMID 25405733, 2014). "In this review, we summarize the most recent findings and discuss the role of PON2/PON3 in atherosclerosis and cancer." (PMID 22666600, 2012). "There is a lack of knowledge of PON2 in general, and further studies on how PON2 is involved in atherosclerosis, how it is associated with vitamin D and how it affects RA patients are warranted." (PMID 30138371, 2018). "It is well accepted that oxidative stress may accelerate the development of atherosclerosis with subsequent up-regulation of cellular antioxidants such as the protein PON2." (PMID 26839578, 2016). "Several studies indicate a major role for PON2 in attenuation of atherosclerosis development." (PMID 26779262, 2015). "The antioxidant paraoxonase 2 (PON-2) is also abundantly expressed in the ITA, whereas its levels decline in carotids as atherosclerosis progresses." (PMID 41584272, 2025). "Search strings included combinations of “PON”, “paraoxonase”, “PON1”, “PON2”, and “PON3” together with terms such as “animal models”, “cancer”, “Atherosclerosis”, and “MASLD”." (PMID 41303537, 2025). "Human enzymes paraoxonase-2 (PON2) and PON3, located on the inner mitochondrial membrane, can also be an interesting candidate for antioxidant therapy of atherosclerosis." (PMID 34017868, 2021). "The human enzymes paraoxonase-2 (PON2) and PON3 are intracellular enzymes with established antioxidative effects and protective functions against atherosclerosis." (PMID 22666600, 2012). "In conclusion, PON2 and PON3 reduce oxidative stress and inflammation and thus act as central regulators of diseases, including cancer and atherosclerosis." (PMID 22666600, 2012). "In addition, the interacting proteins identified in our study provide a better way to understand the function of ASGR1, and PON2 is a hopeful target to inhibit ASGR1 and prevent atherosclerosis." (PMID 39055948, 2024).
atherosclerosis (continued). "One thus may speculate whether the known antiatherogenic potential of PON2 results from its effect on CHOP when considering its linkage to atherosclerosis." (PMID 33562328, 2021). "Additionally, the antioxidant protein paraoxonase-2 (PON2) is involved in the control of oxidative stress, reduction of inflammation, and protection against atherosclerosis." (PMID 35052592, 2021). "The paraoxonases (PON) are a group of antioxidant enzymes, termed PON1, PON2, and PON3 that protect lipoproteins and cells from peroxidation and, as such, may be involved in protection against the atherosclerosis process." (PMID 25993297, 2015). "Although PON2 and PON3 also synthesize paraoxonase proteins, PON2 is not excreted into the blood and any effect by either protein on atherosclerosis or cardiovascular disease is small." (PMID 22577559, 2012). "Moreover, in animal models, both PON2 and PON3 have been shown to abrogate the development of atherosclerosis." (PMID 22666600, 2012). "Here we review studies reporting PON2/PON3 deregulations in cancer, summarize most recent findings on their anti-oxidative and antiapoptotic mechanisms, and discuss how this could be used in putative future therapies to target atherosclerosis and cancer." (PMID 22666600, 2012).
Obesity (13 papers, 2009 to 2025). Accumulation of substantial excess body fat. "underscore the association between PON2 deficiency and heightened susceptibility to diet-induced obesity." (PMID 39411310, 2024). "Similar to one of the possible mechanism of PON2, obesity is a risk factor for many metabolic diseases and even cancer." (PMID 32698306, 2020). "For example, synergistic effects between the PON2 Ala148Gly polymorphism and obesity were found in the risk of T2DM." (PMID 30210454, 2018). "Studies have demonstrated that PON2 deficiency is associated with the drop of energy expenditure and oxygen consumption, which may be the underlying cause of obesity, while it is well known that obesity is an important risk factor for NAFLD." (PMID 32698306, 2020). "In this report, we demonstrated that PON2-def mice are more susceptible to diet-induced obesity." (PMID 30641857, 2019). "The PON2-def mice exhibited decreased energy expenditure and oxygen consumption with no change in food consumption as compared to the WT mice, suggesting that decreased energy expenditure may be the underlying cause of obesity observed in the PON2-def mice." (PMID 30641857, 2019). "The paraoxonase (PON) gene family (including PON1, PON2, and PON3), is known for its anti-oxidative and anti-inflammatory properties, protecting against metabolic diseases such as obesity and metabolic dysfunction-associated steatotic liver disease (MASLD)." (PMID 39334710, 2024). "We found two haplotypes associated with obesity by BMI (in GPX3 and in GPX5 and GPX6) and five haplotypes associated with obesity by PBF (in GPX3, in PON1, and in PON2 and PON3)." (PMID 32752212, 2020). "Another group of relevant antioxidant enzymes associated with obesity is the paraoxonase family (PON1, PON2, PON3), among which PON1 is the most studied one." (PMID 32752212, 2020). "The other four haplotypes were associated with obesity when it was classified by BFP; one of them in GPX3, two others in PON1, and the last one in PON2 and PON3." (PMID 32752212, 2020). "PON2-def mice had increased fasting insulin levels and impaired glucose tolerance after diet-induced obesity." (PMID 30641857, 2019). "Additionally, analysis of rare variants reveals an association with obesity for PON1 and MASLD-related liver fibrosis for PON2." (PMID 39334710, 2024). "For PON2, there have not been consistent associations to either obesity or body weight features in PON2 knockout mice, which is reflected by our study’s lack of genetic association." (PMID 39334710, 2024). "Paraoxonase 2 (PON2), a member of the paraoxonase gene family, was wildly expressed and localized to the nuclear envelope, endoplasmic reticulum, and mitochondria, showing a causal relationship between mitochondrial dysfunction and obesity in mice and humans." (PMID 32698306, 2020). "Given that PON2 reduces oxidative stress-mediated toxicity, it is possible that increasing its levels in the airway epithelial cells could provide therapeutic benefits to subjects with obesity and asthma." (PMID 35286330, 2022). "Therefore, we conclude that the increased ER stress and mitochondrial dysfunction associated with PON2 deficiency are likely the underlying mechanisms leading to decreased beiging and energy expenditure, and increased adipocyte hypertrophy and obesity observed in the PON2-def mice." (PMID 30641857, 2019). "Airway epithelial expression of the antioxidant enzyme Paraoxonase 2 (PON2) is decreased in a well-recognized population of people with T2-low asthma and people with obesity and asthma." (PMID 39594475, 2024). "In this research, three haplotypes; two in PON1, and one PON2 and PON3, were found to be risks factor for obesity." (PMID 32752212, 2020).
bladder cancer (10 papers, 2017 to 2025). "Conversely, overexpression of PON2 is associated with aggressive phenotypes and poor prognosis in melanoma, bladder carcinoma, and basal cell carcinoma." (PMID 40794328, 2025). "Moreover, the effect of PON2 overexpression on tumor cell proliferation and susceptibility to oxidative stress was investigated in human bladder cancer cell line T24." (PMID 28430636, 2017). "Finally, the effect of PON2 overexpression on tumor cell proliferation and susceptibility to oxidative stress was investigated in human bladder cancer cell line T24." (PMID 28430636, 2017). "Temporary overexpression of PON2 in bladder cancer cells suppressed ROS formation after treatment with tert-butyl hydroperoxide (TBHP)." (PMID 40794328, 2025). "Significant PON2 overexpression was additionally identified in clinical samples from multiple kinds of malignancies as well as bladder cancer cell lines." (PMID 40794328, 2025). "HeLa cells overexpressing PON2 are resistant to hydrogen peroxide-induced oxidative stress, while bladder cancer cells with transient PON2 overexpression show reduced ROS generation upon tert-butyl hydroperoxide treatment." (PMID 40794328, 2025). "PON2 knockdown and overexpression were induced in T24 human bladder cancer cells further treated with chemotherapeutic drugs." (PMID 32093309, 2020). "T24 bladder cancer cells were transfected with plasmids inducing paraoxonase-2 silencing or overexpression." (PMID 32093309, 2020). "For example, paraoxonase-2 (PON2) mRNA levels in urinary exfoliated cells from bladder cancer patients can be used as a biomarker." (PMID 30769831, 2019). "Enhanced PON2 and increased ROS in T24 bladder cancer cells treated with CSE may be operating as a defence mechanism against CSE-induced apoptosis." (PMID 40794328, 2025). "The increased expression of PON2 in bladder cancer may contribute to apoptotic escape of tumour cells." (PMID 33923108, 2021). "Similarly, in vitro studies confirmed that the human urinary bladder cancer cell line T24 with induced PON2 overexpression showed an increased cell proliferation." (PMID 33923108, 2021). "Moreover, preliminary results obtained from analyses performed on bladder cancer cell lines seemed to suggest that PON2 is able to promote cell proliferation and resistance to oxidative stress." (PMID 32093309, 2020). "Analogously, PON2 knockdown and overexpression were induced in the T24 BC cell line and the data reported clearly demonstrated that the enzyme was able to promote bladder cancer cell viability, migration, and resistance to treatment with the chemotherapeutic drugs cisplatin and gemcitabine." (PMID 33297311, 2020). "However, several studies showed that PON2 expression was obviously increased in gastric cancer and bladder cancer tissues compared with normal tissue samples." (PMID 32802843, 2020). "Indeed, PON2 downregulation led to an increase of ROS levels in T24 bladder cancer cells treated with chemotherapeutic agents." (PMID 32093309, 2020). "Our results, although obtained from analyses performed on a limited cohort of patients, indicate that PON2 may represent a potential molecular biomarker for bladder cancer." (PMID 28430636, 2017). "The results obtained showed that PON2 could represent a molecular biomarker for bladder cancer and suggest a potential role of the enzyme as a prognostic factor for this neoplasm." (PMID 28430636, 2017). "The aim of this study is to investigate the physio-pathological role of PON2 in bladder cancer." (PMID 28430636, 2017). "The aim of this study is to investigate the role of PON2 in bladder cancer (BC)." (PMID 28430636, 2017). "Bladder cancer, lung adenocarcinoma, melanoma, leukaemia, and glioblastoma currently show the most robust evidence for PON2 as a therapeutic target, given the strong correlation between PON2 activity, cell survival, and chemoresistance, and the clear effects of its knockdown." (PMID 40794328, 2025).
bladder cancer (continued). "Furthermore, the prognostic value of PON2 expression was also explored in patients with bladder cancer, which revealed that PON2 was upregulated in early-stage tumors and fell in later-stage tumors, suggesting a potentially important role for PON2 in different stages of tumorigenesis." (PMID 37337025, 2023).